TERT (telomerase reverse transcriptase)
Diseases named in the same sentence as TERT in open-access papers (continued):
Sharing a sentence is not in itself a finding about the gene and the disease.
cancer (continued). "TERT is the rate-limiting component of the telomerase complex, and its expression, usually absent in normal somatic cells, is detectable in ~90% of human malignancies, allowing cancer cells to overcome the replicative crisis caused by telomere attrition." (PMID 37345011, 2023). "In recent studies, new staging/risk stratification systems or classifications of DTC incorporating TERT promoter mutation have shown improved predictability of recurrence or cancer-specific survival (CSS), which emphasized the prognostic value of TERT promoter mutations in DTC." (PMID 37948420, 2023). "Also in line with this, TERT has been found overexpressed and mutated in multiple human cancers, as well as in mouse tumors." (PMID 37085672, 2023). "All tumors detected with BRAF V600E and/or TERT promoter variants, whether at low or high VAFs, received a definitive cancer diagnosis." (PMID 37505499, 2023). "Besides that, the combined genotypes of TERT (rs2736098*G/A + rs2736100*T/T) and TERT (rs2736098*A/A + rs2736100*G/G) were statistically significant with an elevated risk of HCC compared to cancer-free controls [p-value = 0.004 and 0.047, respectively]." (PMID 37884663, 2023). "In our work, we used bioinformatics analysis to determine the distribution of G4 motifs in TERT promoters, as well as the stability of their composition and sequence across mammalian species of different orders, since the risk of developing cancer is better described in mammals." (PMID 37511853, 2023). "Furthermore, the TERT promoter mutations contribute to the aggressive nature of GBM by allowing the cancer cells to develop resistance to treatment, leading to a higher risk of relapse and reduced survival rates." (PMID 37830090, 2023). "TERT has been shown to exhibit multiple biological activities, independently of its role in telomere maintenance, acting as a transcriptional regulator modulating the expression of genes in several signal pathways implicated in the hallmarks of cancer." (PMID 37296851, 2023). "Mutations in the TERT promoter commonly occur in malignant tumors." (PMID 38136323, 2023). "Indeed, the TERT promoter region has been described as one of the “most frequently mutated non-coding cancer driver”." (PMID 37993930, 2023). "SNPs at the WNT and TERT loci may be linked to cancer formation more directly, because they are genes that are involved in the cell cycle and senescence." (PMID 38163482, 2023). "By contrast, ATRX loss (via ATRX mutations) and TERT activation (via TERT amplification or TERTp mutations) often show mutual exclusivity in various cancers, awaiting a similar confirmation in CM by future studies concurrently analyzing both of these genes for genetic alterations." (PMID 37761808, 2023). "Use the base editing function of CRISPR system to reduce the transcription and protein expression of TERT, and induce the aging and proliferation stagnation of cancer cells, which verifies the feasibility of activated TERT promoter mutation as a cancer-specific therapeutic target." (PMID 37519297, 2023). "Similarly, several studies have described a high percentage of cancer patients, including BC patients, with the TERT c.1-124C>T mutation." (PMID 38068899, 2023). "TERT mutation is a hallmark of cancer and is often used as a diagnostic and prognostic marker." (PMID 38054695, 2023). "These evidences demonstrate that Asian populations and patients with LUAD may have longer telomeres, thereby triggering the risk of cancer, and TERT rs2736100 has a higher value as a genetic marker for diagnosing the pathogenesis of LUAD than LUSC." (PMID 37582820, 2023). "TERT promoter mutations are the most frequent non-coding hotspot alteration in human cancers." (PMID 38201248, 2023). "Mutations in the core promoter of the TERT gene are exceptionally high in many cancer types and may represent specific targets for new therapies." (PMID 38033865, 2023).
cancer (continued). "Mechanisms of telomerase reactivation in cancer cells include complex molecular changes such as chromosomal translocations, TERT gene amplifications, TERT structural variants, transcription binding factors, TERT promoter mutations and spatial chromatin arrangements." (PMID 38033865, 2023). "Based on these results, we infer that TERT -146 may be one of the causal mutations during the development of cancer." (PMID 35053139, 2022). "In addition, the nuclear accumulation of TERT mRNA occurs frequently in cancer cells, and intron retention is identified as a underlying mechanism." (PMID 36713366, 2022). "For cancer cells with TERT biallelic‐expression, both alleles display similar methylation patterns." (PMID 36394204, 2022). "TERT promoter mutations were rare in PTCs but high-risk and highly prevalent in advanced cancers." (PMID 36713542, 2022). "Importantly, numerous cancer types harbor monoallelic TERT promoter mutations that create de novo TF binding sites, namely for members of the ETS family of TFs." (PMID 35159075, 2022). "Simultaneously, gene editing technology based on CRISPR interference and programmable base editing seems to be a very useful approach and might validate activating TERT promoter mutations as a cancer-specific therapy." (PMID 36361634, 2022). "Alterations of the TERT gene such as “hotspot” promoter mutations, amplifications and promoter rearrangements have been associated with increased TERT expression and these alterations have been frequently seen in multiple cancer types." (PMID 34549366, 2022). "However, in ~90% of human cancers, the normally silent human TERT gene (hTERT), encoding the human telomerase catalytic subunit, is activated or upregulated." (PMID 35892638, 2022). "Besides, ETS1/2 heterodimerized with p52 in the C250T region and synergistically activated the expression of the TERT gene, thus proving the atypical role of NFκB in the activation of telomerase in cancer cells with TERT promoter mutations." (PMID 35903534, 2022). "Among them, TERT promoter mutations are particularly common in various cancers." (PMID 35559034, 2022). "Genome-wide association studies have identified multiple variants at the TERT locus, which are associated with the lengths of telomeres and risk of several cancers strongly suggesting that this locus is a common susceptibility locus for many human cancers." (PMID 35135543, 2022). "Therefore, telomerase/TERT repression by inhibiting GABPB1 expression was proposed as a therapeutic strategy against cancer carrying a mutated TERT promoter." (PMID 35326537, 2022). "Reverting TERT promoter mutation by NG-ABEmax may be a safe and effective potential cancer gene therapy targeting the TERT promoter." (PMID 35053139, 2022). "Human Telomerase Reverse Transcriptase (hTERT), a hallmark of cancer, could act as an optimal TAA candidate." (PMID 36361679, 2022). "Furthermore, somatic mutations of the TERT promoter are observed in 70% of solid tumors, indicating that telomerase abundance is critical for cancer initiation and progression." (PMID 35892638, 2022). "Several cancers are reported to harbor frequent mutations in the TERT promoter region." (PMID 35135543, 2022). "Thus, in mono-allelically expressing wild-type cancer cell lines, high methylation levels of the TERT distal promoter associated not only with the silent alleles, but also with the active ones." (PMID 36011010, 2022). "Notably, several cancer driver genes are located in these regions of increased susceptibility, such as TERT, thereby increasing its mutagenic potential." (PMID 34983823, 2022). "To test if disruption of the highly methylated TERT distal promoter would perturb TERT expression, we treated four mono-allelically expressing wild-type cell lines and seven genetically altered cancer cell lines for comparison (five with point mutations and two with rearrangement)." (PMID 36011010, 2022).
cancer (continued). "The recent mapping of cancer genomic landscapes has unravelled novel mechanisms to activate TERT transcription, which includes rearrangements or amplification of the TERT loci, and recurrent TERT promoter mutations." (PMID 36394204, 2022). "TERT expression is downregulated in most of somatic cells upon differentiation due to epigenetic silencing with a few exceptions but its expression reactivated in most of the cancer cells, partially because of core promoter mutations." (PMID 35669414, 2022). "In the present study, we have shown that h‐TERT‐RdRP activity, which is a non‐telomelic function of hTERT, is closely associated with aggressiveness and poorer prognosis via the regulation of proliferation and differentiation in cancer." (PMID 35094384, 2022). "A previous report has shown that ΔNp63α induces TERT promoter activation and RNA splicing in mice; therefore, p‐hTERT expression in cancers might be closely associated with squamous differentiation." (PMID 35094384, 2022). "These TERT promoter mutations are thought to act as driver mutations because they confer a fitness advantage and thus may promote or drive cancer progression." (PMID 35920280, 2022). "Facing the cancer telomerase issue from a different perspective, a couple of groups used Cas9 to edit the promoter sequences of TERT, providing a useful tool for studying telomerase biology and understanding the molecular basis by which cancer-associated TERT mutations impact telomerase activity." (PMID 36497228, 2022). "In cancer, telomerase up-regulation is frequently mediated through activating mutations, amplifications, structural variants, and promoter methylation in TERT." (PMID 35740680, 2022). "Importantly, RB1 loss increases opportunities for mutation of several cancer driver genes, most notably the TERT gene, which plays critical roles in carcinogenesis by sustaining proliferative capacity." (PMID 34983823, 2022). "TERT (telomerase reverse transcriptase) encodes a catalytic subunit of telomerase, which is influenced by multiple genetic and epigenetic regulations in many cancers." (PMID 35504036, 2022). "TERT promoter mutations are common in human cancer and confer cellular immortality." (PMID 36130485, 2022). "In cancer cells harboring a heterogenous TERT promoter mutation, the mutant-allele displays the expression-allele methylation profile, and the non-expressing WT allele may have increased TSS methylation and/or reduced UTSS methylation." (PMID 36713366, 2022). "Because these patients were free of cancer, the occurrence of C228T mutation in their lymphocytes dose not result from oncogenic events per se, indicating a causal relationship between shorter dysfunctional telomeres and TERT promoter mutations." (PMID 36713366, 2022). "Previous systematic analysis indicated methylation and mutation of the TERT promoter in 53% and 31%, respectively, of TERT expressing cancer cell lines supporting the concept of a key role for epigenetic alteration associated with TERT dysregulation and cellular transformation." (PMID 33802026, 2021). "In 31% of cancers, TERT reactivation is due to mutations in the TERT promoter." (PMID 34944589, 2021). "Yet, the discovery of driver mutations in the non-coding TERT gene across many cancer types raised the possibility that there may be numerous other non-coding driver mutations." (PMID 34097189, 2021). "CLPTM1L gene may be associated in apoptosis processes and high expressed in cisplatin-resistant cell lines, TERT gene produce catalytic subunit of telomerase, associated with telomere maintaining and usually active in cancer cells." (PMID 33879152, 2021).
cancer (continued). "In addition to regulating cell proliferation and the expression of pro-cancer genes, TERT has also been implicated in modulating inflammatory signals in cancer cells." (PMID 33599797, 2021). "Thus, the C allele improves ZNF148 binding site, which elevates the TERT expression level and, as a consequence, increases the risk of multiple cancer types." (PMID 34208629, 2021). "In the past decade, many studies have sought to identify TERT variants in various types of cancer, as these variants could be the driver of carcinogenesis." (PMID 34440361, 2021). "Mutations to the TERT coding regions might influence telomere length and telomerase activity, which might further lead to substantially elevated cancer-related morbidity." (PMID 34540891, 2021). "Multiple TERT-locus variants at 5p15 have been discovered in association with cancer risk, yet the underlying mechanisms and clinical impacts remain unclear." (PMID 34858826, 2021). "In addition, a series of genetic variants in MICA, MICB, NFKBIL1, SLC6A3, CLPTM1L, and TERT have been found to be associated with the susceptibility and prognosis of different cancer types." (PMID 35003220, 2021). "Overexpression of TERT by its promoter mutation representing late events of the oncogenic process may increase the self-renewal capacity of cancer stem cells and induce poor clinical outcomes." (PMID 33994739, 2021). "Importantly, these de novo sites are very near to the GC-boxes in the core TERT promoter, which provide a unique regulatory mechanism for the reactivation of the TERT gene in cancers harboring TERT promoter mutations." (PMID 33599797, 2021). "Notably, every ten-unit increment of TERT mRNA was associated with a 4% increase in the risk of developing cancer (HR=1.04, 95%C.I." (PMID 34746013, 2021). "Moreover, genome-wide association studies (GWASs) and case–control studies have demonstrated that polymorphisms in TERT are associated with various cancers such as skin cancer, CRC and breast cancer." (PMID 34059744, 2021). "Individually they might just have subtle inhibitory effect on TERT but together they may increase LS patients’ risk of cancer development." (PMID 34059744, 2021). "TERT promoter mutations are frequently detected in various cancers such as skin and glioma." (PMID 34368047, 2021). "Some cancer lineages (e.g., brain, liver, skin, and bladder) frequently acquire recurrent mutations in the TERT promoter (TERTp) region, predominantly at −124 and −146 loci upstream from TERT transcription start site." (PMID 33420056, 2021). "In cancer, somatic DNA alterations extend beyond gene boundaries and impact gene regulation, with one well-known example involving single nucleotide variants (SNVs) in the TERT promoter region, causing overexpression of the gene." (PMID 34788622, 2021). "The cancer tissue was prepared in a paraffin block and sent to another hospital, and this process may affect the detection of TERT promoter mutation." (PMID 34070093, 2021). "In line with this view, it is remarkable that TERT promoter mutations are generally found in solid cancers with relatively low self-renewal rate, while they are rare (<15%) in cancers with high turnover and intrinsic TERT expression, such as hematopoietic, lymphoid, or gastrointestinal malignancies." (PMID 34944589, 2021). "Alterations in BRAF, RAS, RET/PTC, and TERT promoters are assumed as “driver” changes and could be used as diagnostic markers for cancer development." (PMID 34684168, 2021). "The TERT promoter consists of a largely hypomethylated CpG island in somatic cells but these are hypermethylated or partially methylated in association with expression and telomerase activation in many cancer cells." (PMID 33802026, 2021). "Therefore, increased TERT expression and telomerase activity can be detected in close to 90% of human cancers, highlighting the association of the hTERT with the telomerase in the emergence of malignant and aggressive phenotypes." (PMID 34947936, 2021).
cancer (continued). "A meta-analysis reports that among cancer patients with TERT promoter mutations, the rs2853669 T/T genotype confers a worse prognosis, but the modifying role of this SNP in the prognostic value of TERT promoter mutations is still controversial." (PMID 34858860, 2021). "In other cancer types, TERT promoter mutations are associated with older age." (PMID 33755803, 2021). "Genes associated with aggressive phenotype, such as TERT, are generally mutated in both well-differentiated and anaplastic components, suggesting that TERT-mutated carcinomas that are histologically well differentiated possess an intrinsic predisposition to dedifferentiation." (PMID 33543394, 2021). "Our study reported that male patients with TERT mutation may be more likely to benefit from immunotherapy in a multitude of cancers." (PMID 32915164, 2020). "However, an increasing body of evidence supports the notion that most types of cancer cells, among which are skin cancer cells, exhibit an increased TA, mainly due to TERT promoter mutations." (PMID 32899768, 2020). "Reduced methylation in the TERT promoter occurs in cancers that harbor TERT promoter mutations." (PMID 32121056, 2020). "Several studies showed that chromosomal rearrangements at the TERT locus may be associated with cancer development and as was observed, e.g., in the case of neuroblastoma." (PMID 33329574, 2020). "Taken together, these data suggest that some cancers with bi-allelic or hemizygous TERT promoter mutations still maintain a high fraction of methylated alleles, with only the remaining unmethylated alleles being associated with active chromatin and RNA Pol 2 binding." (PMID 32468444, 2020). "For example the mutations in the TERT promoter were found to be associated with cancer progression." (PMID 33092526, 2020). "Therefore, mutation of the TERT promoter cannot be the sole mechanism by which telomerase expression is increased in cancer." (PMID 33024276, 2020). "SNPs in the TERT gene have been associated with outcomes in several cancers." (PMID 33113831, 2020). "TERT somatic mutations are the most common non-coding mutations in human cancer cells." (PMID 33329574, 2020). "Cancers harboring TERT promoter mutations are often more lethal." (PMID 33113965, 2020). "The TERT gene encodes Telomerase, which is responsible for the extension of telomeres, thereby increasing the lifespan of cells or even leading to immortalization, as commonly observed in cancer cells." (PMID 32605217, 2020). "However, non-coding cancer driver mutations are less well-characterized and only a handful of recurrent non-coding mutations, most notably TERT promoter mutations, have been reported." (PMID 32024854, 2020). "In cancer cells, TERTp mutations are generally associated with higher TERT expression level." (PMID 33329574, 2020). "Since TERT mRNA status was associated with age at diagnosis in the malignant tumours, the levels of expression were assessed considering this feature, for both benign and malignant tumours (One-way ANOVA p = 0.0005)." (PMID 32659948, 2020). "In some studies using cancer cells, these treatments caused decreased TERT expression, which may actually be due to demethylation of a downstream CTCF repressor binding site." (PMID 33245585, 2020). "In conclusion, we have identified that TERT mutations are unevenly distributed in different cancer types which may lead to aberrant upregulation of TERT expression in various tumors." (PMID 32810393, 2020). "In contrast to most genes, TERT promoter hypomethylation could be associated to its transcriptional repression in cancer, suggesting that tert promoter sequences may be a binding site for the CTCF/cohesin complex." (PMID 33266037, 2020). "Mutations in the presence of the TERT promoter region have been reported in numerous cancers." (PMID 32047544, 2020). "This study aimed to investigate whether the TERT mutation is a potential predictor of ICI treatment across all cancer types." (PMID 32810393, 2020).